PARG (poly(ADP-ribose) glycohydrolase)
Description:
Poly(ADP-ribose) glycohydrolase that degrades poly(ADP-ribose) by hydrolyzing the ribose-ribose bonds present in poly(ADP-ribose). Mainly acts as an exo-glycohydrolase but can act as an endo-glycohydrolase at low efficiency, releasing poly(ADP-ribose) of different length as well as ADP-ribose monomers. It is however unable to cleave the ester bond between the terminal ADP-ribose and ADP-ribosylated residues, leaving proteins that are mono-ADP-ribosylated. Poly(ADP-ribose) synthesized after DNA damage is only present transiently and is rapidly degraded by PARG. Required to prevent detrimental accumulation of poly(ADP-ribose) upon prolonged replicative stress, while it is not required for recovery from transient replicative stress. Responsible for the prevalence of mono-ADP-ribosylated proteins in cells, thanks to its ability to degrade poly(ADP-ribose) without cleaving the terminal protein-ribose bond. Required for retinoid acid-dependent gene transactivation, probably by removing poly(ADP-ribose) from histone demethylase KDM4D, allowing chromatin derepression at RAR-dependent gene promoters. Involved in the synthesis of ATP in the nucleus, together with PARP1, NMNAT1 and NUDT5. Nuclear ATP generation is required for extensive chromatin remodeling events that are energy-consuming.
Synonyms: PARG99
Tractability: Small molecule: a structure with a bound ligand is known; a high-quality ligand is known. PROTAC: ubiquitination databases record sites on it; its protein half-life has been measured; a small molecule that binds it is known.
Target class: Enzyme; Hydrolase
Chemical probes: PDD00017273 (high quality)
Gene: Protein-coding gene on chromosome 10 (49,815,137 to 49,970,203, reverse strand). Ensembl gene ENSG00000227345.
Subcellular location: Nucleus (Isoform 1); Cytoplasm (Isoform 2); Cytoplasm (Isoform 3); Cytoplasm (Isoform 4); Mitochondrion; Mitochondrion matrix (Isoform 5)
Subcellular location (Human Protein Atlas): Nucleoplasm; Cytosol; Nuclear bodies
Pathways (Reactome):
DNA Repair: POLB-Dependent Long Patch Base Excision Repair
Gene Ontology:
Molecular function: poly(ADP-ribose) glycohydrolase activity; protein binding
Biological process: ATP generation from poly-ADP-D-ribose; base-excision repair, gap-filling; nucleotide-sugar metabolic process; carbohydrate metabolic process; regulation of DNA repair
Cellular component: cytoplasm; cytosol; mitochondrial matrix; mitochondrion; nuclear body; nucleoplasm; nucleus
Genetic constraint (gnomAD): Loss-of-function variants: 7 observed, 25.22 expected, observed/expected ratio (o/e) 0.28, 90% interval 0.16 to 0.52. The upper end of that interval is the gene's LOEUF score, 0.52, which puts it in group 2 of 6, group 1 being the genes least tolerant of losing a copy. Missense variants: 330 observed, 379.52 expected, observed/expected ratio (o/e) 0.87, 90% interval 0.79 to 0.95. Synonymous variants: 135 observed, 142.8 expected, observed/expected ratio (o/e) 0.95, 90% interval 0.82 to 1.09.
Homologues: Orthologues: macaque PARG (98% identical), pig PARG (91% identical), chimpanzee PARG (89% identical), rabbit PARG (88% identical), mouse Parg (87% identical), guinea pig PARG (86% identical), rat Parg (85% identical), tropical clawed frog parg (44% identical), zebrafish parga (37% identical), Drosophila melanogaster Parg (24% identical), Caenorhabditis elegans parg-1 (16% identical), Caenorhabditis elegans parg-2 (14% identical).
Diseases named in the same sentence as PARG in open-access papers:
PARG is named in the same sentence as 77 diseases in open-access papers, as found by Europe PMC text mining. Sharing a sentence is not in itself a finding about the gene and the disease. The quoted sentences say what the papers report.
breast cancer (22 papers, 2012 to 2025). A primary or metastatic malignant neoplasm involving the breast. "In our recent work, we have found that PARG loss is the most frequently detected PARPi-resistance mechanism in mammary tumors from BRCA2-deficient triple-negative breast cancer (TNBC) mouse models." (PMID 38360994, 2024). "In this study, we find that elevated PARG levels are associated with a poor prognosis in breast cancers, especially in HER2-positive and triple-negative subtypes." (PMID 30459355, 2019). "Next, to interrogate the possible clinical relevance of PARG in breast cancer, we evaluated the association of PARG mRNA levels with patient overall survival, first incorporating all breast cancer patients, followed by segregation into molecular subtypes." (PMID 30459355, 2019). "In order to evaluate whether PARG depletion sensitizes cells mutated in BRCA1 by synthetic lethality, we depleted PARG by siRNA in several breast cancer cell lines either wild type or mutated for BRCA1." (PMID 27375368, 2016). "Thus, PARG levels are associated with a poor prognosis in breast cancers." (PMID 30991935, 2019). "They demonstrated that PARG is frequently lost in acquired PARPi-resistant mouse mammary tumors and further revealed that PARG depletion occurs in triple-negative breast and ovarian cancer." (PMID 38578205, 2024). "Experiments have showed that loss of HR proteins such as BRCA1/2 in breast cancer cells stimulate the synthetic lethality of PARG-inhibiting cells, and the PARG inhibitor induces cell death of BRCA mutated or olaparib-resistant breast cancer cells." (PMID 39334297, 2024). "Higher PARG expression were associated with better survival outcome for renal cancer, thyroid cancer and PAM50 Her2 and Luminal B breast cancer subtypes." (PMID 35585513, 2022). "Depletion of the HR proteins BRCA1/2, PALB2, ABRAXAS, and BARD1 in MCF7 breast cancer cells was shown to elicit synthetic lethal interactions with PARG depletion or PARG inhibition (with gallotannin or PDD00017273)." (PMID 32029455, 2020). "The PARG inhibitor COH34 efficiently kills BRCA mutated or olaparib-resistant ovarian and breast cancer cells." (PMID 32029455, 2020). "PARGi or PARG depletion has been observed to be synthetically lethal in BRCA2 depleted and deficient breast cancer cells." (PMID 33005627, 2020). "To explore a role for PARG in metastasis, we took advantage of a well-characterized panel of isogenic murine breast cancer cell lines that differ in their ability to metastasize when implanted into the mammary fat pads of syngeneic mice." (PMID 30459355, 2019). "Overall, our study underscores the oncogenic impact of aberrant protein PARylation and highlights the therapeutic potential of PARG inhibition in breast cancer." (PMID 30459355, 2019). "We first utilized MDA-MB-231 cells because they show high 110 kDa PARG isoform expression and represent a well-characterized model of basal-like breast cancer; a subtype of breast cancer where high PARG expression correlates with poor overall survival." (PMID 30459355, 2019). "Here, we show that PARG expression is elevated in breast cancer and that aberrantly high PARG levels support transformation, tumor outgrowth and metastasis." (PMID 30459355, 2019). "Medication of PARG inhibitor in breast cancer is mainly under preclinical investigation." (PMID 39334297, 2024). "Higher PARG expression is associated with a poor prognosis in breast cancer, particularly in the HER2‐positive and triple‐negative subtypes." (PMID 36053937, 2023). "Indeed, inactivation of BRCA1, BRCA2, PALB2, FAM175A, and BARD1 are synthetic lethal with PARG depletion in MCF7 breast cancer cells due to disruption of HR-mediated DDR." (PMID 30889383, 2019).
breast cancer (continued). "Depletion of PARG significantly impairs the growth and metastasis of triple-negative breast tumours, in both in vitro and in vivo models, thus highlighting the therapeutic potential of PARG inhibition in breast cancer." (PMID 30991935, 2019). "Importantly, abrogation of PARG expression leads to decrease in tumor growth and metastasis of triple-negative models of breast cancer." (PMID 30459355, 2019). "In addition, given the breast cancer focused screen performed here, a full screen of synthetic lethality with PARG inhibitors is warranted." (PMID 28254358, 2017). "We observed an analogous decrease in RPA2 hyperphosphorylation in MDA-MB231 breast cancer cells transiently depleted in PARG by siRNA and treated with 2 mM HU for 24 h, and this hyperphosphorylation was restored in the presence of a PARP inhibitor (data not shown)." (PMID 24906880, 2014). "However, our data here shows that the silencing of PARG by RNAi leads to increased breast cancer cell survival." (PMID 22839996, 2012). "It has been reported that depletion of the HR proteins such as BRCA1/2 in breast cancer cells could stimulate synthetic lethality in PARG‐inhibited cells, and that COH34, a PARG inhibitor, is able to induce cell death of ovarian and breast cancers with BRCA mutations or resistance to olaparib." (PMID 34977872, 2021). "However, here in MCF-7 breast cancer cells, while PARG inhibition resulted in a reduced G2/M population and a reduced mitotic index, those cells in mitosis had an increased incidence of aberrant mitotic figures and a higher proportion of mitotic cells were in metaphase than in control cells." (PMID 29179156, 2018). "Interestingly, the pharmacologic inhibition of caspase activity in PARG-silenced breast cancer cells led to increased cell death after chemotherapy, which indicates that an alternative cell death pathway is activated due to elevated PAR levels and caspase inhibition." (PMID 22839996, 2012). "Therefore, the specific inhibition of the nuclear PARG isoform may be required to optimize cell death in breast cancer cells in response to chemotherapeutic treatments." (PMID 22839996, 2012). "Previous studies demonstrated that PARG silencers and PARG inhibitors, such as PDD00017273, inhibit tumor cell growth and increase radiosensitization in the MCF‐7 breast cancer cell line." (PMID 36053937, 2023). "This is consistent with patient data correlating PARG expression with poor prognosis in ER-negative triple-negative and HER2+ breast cancers." (PMID 30459355, 2019). "We previously established that 0.3 μM of the PARG inhibitor PDD00017273 is the optimum dose for inhibition of endogenous PARG activity, with minimal cell killing in the breast cancer cell line MCF-7." (PMID 29179156, 2018). "Synthetic lethality has also be reported with other HR related proteins including BRCA1, PALB2, FAM175A (ABRAXAS), and BARD1 in breast cancer cells where a more specific PARGi, PDD00017273, was used and on-target effects validated using two independent PARG siRNA." (PMID 33005627, 2020). "Thus, we next investigated the effects of the silencing of PARG, the primary enzyme that catalyzes the hydrolysis of PAR, on PAR levels in MDA-MB-231 breast cancer cells." (PMID 22839996, 2012). "In tumour cells lacking HR proficiency, PARG inhibition appears to cause synthetic lethality, in a similar vein to the archetypal synthetic lethality of PARP inhibitors in BRCA1/2-deficient breast cancer cells." (PMID 38368415, 2024). "Thus, PARG inhibition partially rescued PJ34 mediated downregulation of CCL2, suggesting a positive correlation between CCL2 transcription and PARylation in the breast cancer cells." (PMID 32455851, 2020). "We also measured PAR accumulation in breast cancer cells injected into C57/BL6 mice without establishing xenograft tumors over a 24-hr time course post injection, with or without PARG inhibitor treatment." (PMID 35476036, 2022).
breast cancer (continued). "Of the six tested breast cancer lines, only one BRCA‐proficient cell line was sensitive to PARG inhibitor PDD00017273, whereas five cell lines failed to respond to PDD00017273 including those with BRCA mutations." (PMID 34977872, 2021).
ovarian carcinoma (20 papers, 2016 to 2025). A malignant neoplasm originating from the surface ovarian epithelium. "Our results, however, support the potential use of PARG inhibitors as viable, complementary strategy to induce cell lethality and invasion arrest in ovarian cancer and potentially other HR-deficient cancers." (PMID 34778062, 2021). "Further evidence of the importance of PARG during replication stress comes from ovarian cancer cells where loss of expression of key replication proteins (e.g., Timeless, Hus1 and RFC2), led to sensitivity to PARGi." (PMID 33005627, 2020). "Since currently available PARG inhibitors are not satisfying so far, questioned either for their specificity or for their cell permeability, we evaluated the impact of PARG depletion by siRNA on cell survival of several breast and ovarian cancer cell lines either proficient or deficient in BRCA1." (PMID 27375368, 2016). "Therefore endogenous PARG levels could predict Olaparib response in HR deficient as well as in polβ deficient ovarian cancer cells." (PMID 33674744, 2021). "Here, we explore the potential impact of the combined therapeutic approach involving ARH3 and PARG inhibition on cancer cells, focusing on ovarian cancer cells because of the crucial role of PARylation on ovarian cancer resistance to chemotherapeutics [9,35,]." (PMID 39615107, 2025). "Our findings align with previous studies demonstrating that PARG depletion enhances the efficacy of chemotherapeutic agents in melanoma, ovarian cancer, glioblastoma, and head and neck cancer." (PMID 41451844, 2025). "To understand PARG activity dependency, we analysed Timeless model systems and intrinsically sensitive ovarian cancer cells." (PMID 39015544, 2024). "We further performed an IHC assay to detect PARG expression in breast and ovarian cancer TMA samples." (PMID 38578205, 2024). "Accordingly, hallmarks of replication catastrophe have been proposed as a biomarker, for instance, to predict the sensitivity to poly(ADP-ribose) glycohydrolase (PARG) inhibitors in subsets of ovarian cancer." (PMID 37445667, 2023). "We discover that a subset of ovarian cancers are intrinsically sensitive to pharmacological PARG blockade, including drug-resistant disease, underpinned by a common mechanism of replication catastrophe." (PMID 34656146, 2021). "This study shows that in ovarian cancer, PARG inhibition reduces cell migration, suppresses clone formation, and promotes G2/M cell cycle arrest and cell death, alone and in combination with PARPi and Cisplatin." (PMID 34778062, 2021). "This study aims to evaluate the effect of a PARG inhibitor (PARGi) on epithelial ovarian cancer (OC) cell lines, alone and in combination with a PARP inhibitor (PARPi) and/or Cisplatin." (PMID 34778062, 2021). "PARG inhibition appears as a complementary strategy to PARP inhibition in the treatment of ovarian cancer, especially in the presence of homologous recombination defects." (PMID 34778062, 2021). "Another added value of our study include: 1- this study opens a window to the potential clinical benefit of PARGi as we report on high expression of PARG in ovarian cancer cells using novel analysis of online databases and in patient derived samples." (PMID 34778062, 2021). "And finally, does PARG inhibition show efficacy in ovarian cancer cells resistant to PARP inhibitors?" (PMID 30889383, 2019). "Here, we show that a subset of ovarian cancer cell lines and ex vivo models derived from patient biopsies are sensitive to a poly(ADP-ribose) glycohydrolase (PARG) inhibitor." (PMID 30889383, 2019). "Because PARG and PARP inhibitor sensitivity are mutually exclusive, our observations demonstrate that PARG inhibitors have therapeutic potential to complement PARP inhibitor strategies in the treatment of ovarian cancer." (PMID 30889383, 2019). "We show that a subset of preclinical ovarian cancer models is sensitive to pharmacological inhibition of PARG, the glycohydrolase that counterbalances PARP activity." (PMID 30889383, 2019).
ovarian carcinoma (continued). "(c) Ranked PARG expression level in ovarian cancer cell lines based on the CCLE database." (PMID 38578205, 2024). "To further test our hypothesis, we ranked the PARG mRNA level in several ovarian cancer cell lines using the CCLE database." (PMID 38578205, 2024). "It is reported that ovarian cancer cells show differential sensitivity to PARG and PARP inhibitors, and cells with replication vulnerability show persistent replication fork stalling and replication catastrophe, with treatment of the PARG inhibitor and sensitization to CHK1 inhibitor." (PMID 32344695, 2020). "To determine whether PARG inhibitors might open up therapeutic opportunities in ovarian cancer, we assembled a panel of six ovarian cancer cell lines with genomic features that reflect HGSOC, namely Kuramochi, OVSAHO, COV362, COV318, CAOV3, and OVCAR3." (PMID 30889383, 2019). "Thus, we conclude that the mechanistic insight derived from the analysis of established cell lines does extend to clinically relevant models of ovarian cancer, and that PARG inhibitors open up opportunities to treat patients with ovarian cancer." (PMID 30889383, 2019). "Thus, chemotherapy-induced replication stress can potentially sensitize additional ovarian cancer cells to PARG inhibition." (PMID 30889383, 2019). "Therefore, PARG inhibitors may complement PARPi action, and combination treatment has been shown to be synergistic in ovarian cancer cells." (PMID 36849518, 2023). "Given that PARG suppression was indicated as one of the mechanisms of PARPi resistance in BRCA2-deficient cancer cells, we additionally explored the effect of TARG1 loss on PARGi sensitivity in BRCA2-deficient ovarian cancer PEO1 cells and observed a similar sensitivity phenotype." (PMID 37676774, 2023). "The data suggest that PARG may have prognostic significance in ovarian cancers." (PMID 33674744, 2021). "Consistent with this possibility, of the five ovarian cancer cell lines ranking highest for downregulation of DNA replication genes, three are sensitive to PARG inhibition, suggesting that a gene expression signature may have potential as a predictive biomarker." (PMID 30889383, 2019). "We identified an ovarian cancer cell line, RMUGS, which has low PARG expression, similar to that observed in another known PARGi-sensitive cell line, KURAMOCHI." (PMID 38578205, 2024). "As for other pathways involving PARP1 and PARylation, inhibitors of PARG (enzyme that hydrolyzes PAR) have been exploited in cancer types with different sources of genomic instability, such as ovarian cancer." (PMID 36849518, 2023). "show that ovarian cancer cells respond to inhibition of poly(ADP-ribose) (PAR) polymerase and inhibition of PAR glycohydrolase (PARG) differently; sensitivity to the latter is due to persistent fork stalling and replication catastrophe." (PMID 30889383, 2019). "This provides a compelling rationale for combining PARG and WEE1 inhibitors as a therapeutic strategy in ovarian cancer." (PMID 30889383, 2019). "To better understand the molecular determinants of PARG inhibitor sensitivity, we took a multifaceted approach, analysing (a) model systems engineered to be PARGi sensitive via inhibition of TIMELESS, and (b) intrinsically sensitive ovarian cancer cells." (PMID 39015544, 2024). "In addition, we examined PARG expression by the IHC assay in commercial TMA samples and uncovered a fraction of breast and ovarian cancers with no detectable or low PARG expression." (PMID 38578205, 2024). "Interestingly, about 5% to 40% of these breast or ovarian cancer tumor samples showed low expression levels of PARG, some even showed no detectable level of PARG, compared with those in normal tissue samples." (PMID 38578205, 2024). "Because PARP and PARG inhibitor sensitivity does not overlap, PARG inhibitors could offer an additional treatment strategy for ovarian cancer." (PMID 30889383, 2019).